IL1B (interleukin 1 beta)
Diseases named in the same sentence as IL1B in open-access papers (continued):
Sharing a sentence is not in itself a finding about the gene and the disease.
tumor (continued). "Use of neutralizing antibodies against IL-1β can modulate the maturation, proliferation, and migration abilities of TAMs, which may retard tumor growth." (PMID 34150748, 2021). "Here, we demonstrated that both SEVs are also able to induce a significant upregulation of NF-kB at the protein level, leading to an increase in TNF-α and IL1β expressions; this contributes to the creation of an inflammatory microenvironment able to support and to enhance tumor progression." (PMID 34829995, 2021). "Recent evidence has also shown that the nature of tumor cells, in particular their low or high aggressiveness, dictates the type of interactions with MSCs and notably the production of multiple chemokines and prostaglandin E2 upon release of IL-1β by tumor cells." (PMID 34858421, 2021). "We speculate that this may further support our hypothesis that tumour-derived IL-1B restores an anti-tumour immune response." (PMID 34290237, 2021). "Together, these findings suggest that inflammasomes may attenuate tumour progression through IL-1β production and recruitment of TANs." (PMID 33918087, 2021). "IL1β is another crucial molecule present in the SASP with a relevant pro-tumor activity." (PMID 34447383, 2021). "Indeed, IL-1β signaling in dendritic cells has been shown to be critical for the induction of radiation-induced anti-tumor immune responses." (PMID 34638239, 2021). "Of note, IL1β and IL8 have both been linked to tumor cell- and immune cell-associated senescence, and acquisition of a pro-inflammatory secretory phenotype (SASP), which would favor further genetic and chromosomal instability, with relatively limited effects on bone metabolism." (PMID 33810169, 2021). "Moreover, using an MTT proliferation assay we found that tumour cells overexpressing IL1R1 displayed reduced proliferation compared to control cells when stimulated with exogenous IL-1B." (PMID 34290237, 2021). "Moreover, in most patient tumors TNFα and IL-1β were concomitantly expressed at the tumor site and in patient materials." (PMID 34072893, 2021). "Moreover, both IL-1β and IL-6 were upregulated in the tumour sample and surgical margin in comparison to the calibrator (RQ > 1)." (PMID 33658555, 2021). "In addition, cancer cells induce IL-22 production by memory CD4+T cells via IL-1β in order to promote tumor growth." (PMID 33846436, 2021). "IL-1β is a common cytokine, which has a two-way effect on the tumor." (PMID 34422050, 2021). "In addition, neutrophils can also motivate metastasis formation via inhibiting natural killer function and facilitating the extravasation of tumor cells through the secretion of IL1β and matrix metalloproteinases." (PMID 34858812, 2021). "We observed the concomitant expression of anti-tumor factors (Il1b, Il13, Ccl7, Il2)." (PMID 34578328, 2021). "Furthermore, Il1β induces Il6 production, which promotes sustained, excessive inflammation, fostering a pro-tumor immune environment." (PMID 33441763, 2021). "IL-1β is one of the most abundant and influential cytokine of tumor microenvironment." (PMID 34070682, 2021). "Moreover, IL-1B produced by macrophages infiltrating the primary tumour, initiates a systemic neutrophilic inflammatory response that ultimately results in CD8+ T cell inhibition, immunosuppression and metastasis to the lungs." (PMID 34290237, 2021). "MiR-19a mimic was also administered in the AOM/DSS-induced CRC mice and induced pro-inflammatory cytokines (IL-6, TNF-α, IL-1β and IL-17a), tumor proliferation marker (Ki-67) and NF-κB signaling markers (p-P65 and COX-2) via targeting TNF-α-induced protein 3 (TNFAIP3)." (PMID 33921348, 2021). "Acute and transient inflammation may inhibit tumor growth by upregulating pro-inflammatory cytokines such as TNFα, IL-1β, and IL-6 that are part of the initial inflammatory cascade and recruit other downstream targets to enhance anti-tumor responses." (PMID 34975408, 2021).
tumor (continued). "Ajulemic acid (AJA) is a synthetic cannabinoid preferentially binding to CB2 receptors, which might play a key role in inhibiting tumor progression through impeding IL-1β release responsible for inflammation in the microenvironment of the tumor." (PMID 34361704, 2021). "We explored other protumorogenic properties, such as migration, on which IL1β and their soluble targets could be altering the crosstalk between tumor cells and fibroblasts." (PMID 34066976, 2021). "Besides direct transcribing cell proliferation‐related genes, NF‐κB also induces the expression of proinflammatory cytokines such as IL‐1β, IL‐6, and TNFα, which play a key role in the NF‐κB‐dependent tumor cell proliferation." (PMID 34977871, 2021). "IL-1β is abundant in the tumor microenvironment and is secreted by innate immune cells." (PMID 34944905, 2021). "Thus, this study provides insights into the role of NOX2-derived ROS in driving tumor colonization through a neutrophil and IL-1β-dependent pathway." (PMID 34257370, 2021). "Furthermore, except for MIP1α and IL-1β expression in carcinoma tissues, PI3KγHE mice showed similar mRNA levels of markers of inflammation in normal liver and tumours." (PMID 34704005, 2021). "During ICD, some molecules, such as ATP, are released from tumor dying cells as danger signals and activate, through the P2X7 receptor, the inflammasome in macrophages, inducing the maturation and the release of IL-1β that promotes tumor antigens presentation to dendritic cells." (PMID 33477845, 2021). "A botanical drug called APG-157 containing multiple polyphenols suppressed tumor cells due to its antioxidant and anti-inflammatory properties, as demonstrated by reduced IL-1β, IL-6, and IL-8 concentrations in the salivary supernatant fluid of oral cancer patients." (PMID 34950252, 2021). "Thus, CD8 T cells activate the NLRP3 in antigen-presenting cells (APCs) that promote IL1β maturation and contribute to the induction of antigen-specific anti-tumor immunity amplifying the CD8 effector functions." (PMID 34685542, 2021). "It remains to be explored whether the enhanced tumor-killing capacity of plinabulin-polarized TAMs is exclusively contact-dependent and/or mediated by soluble factors, such as IL-1β." (PMID 33747968, 2021). "Similar to IL-1β, upregulation of IL-18 may facilitate tumour immune escape by recruiting MDSCs and promoting metastatic ability in tumour cells via upregulation of the vascular endothelial growth factor (VEGF)." (PMID 33918087, 2021). "In this context, targeting tumor and host-derived IL-1β with anakinra improved anti-PD-1 therapy." (PMID 33840390, 2021). "In these models, we found that inhibition of IL1R1 did not affect primary tumour growth, whereas inhibition of IL-1B resulted in increased primary tumour growth, therefore recapitulating the effect that we had previously seen following pharmacological inhibition of IL-1B signalling." (PMID 34290237, 2021). "Researchers injected BMSCs into these mice models and observed reduced tumor cells which were derived by alleviated expression of proinflammatory cytokines such as TNFa, IL-6, and IL-1b and reduction of STAT3 activation by phosphorylation in colorectal tissues." (PMID 34249257, 2021). "IL-1β confers stem-cell-like ability of tumor cells to enhance their metastatic potential." (PMID 34602858, 2021). "In this study, we show that tumor-associated neutrophils expressed ICAM-1 and IL-1β in the lungs." (PMID 34257370, 2021). "To find out if the source of IL1β that stimulate the fibroblasts in a paracrine form could be the interleukin generated by the tumor cells, we silenced the expression of IL1β in the HT29 cells." (PMID 34066976, 2021). "Our results shows that IL1β is overexpressed in cocultured tumor cells." (PMID 34066976, 2021). "Also, a great many inflammation-inducing cytokines harbor potent pro-tumor ability, comprised of IL-1β, IL-5 and MCP-1." (PMID 34016791, 2021).
tumor (continued). "Indeed, the IL-1β secreted in the tumor microenvironment induces the secretion of IL-17 through its effect on CD4 T cells, by driving the differentiation and expansion of Th17 cells, which promote angiogenesis and tumor growth via the STAT3 signaling pathway." (PMID 33498483, 2021). "In addition to macrophages and DCs, it has also been reported that IL‐1β induces NF‐κB activation in MDSCs to suppress the function of tumor microenvironment (TME), leading to tumor proliferation." (PMID 34977871, 2021). "Then, we determined the effects of continuous TNFα + IL-1β stimulation on tumor cell growth." (PMID 34072893, 2021). "Moreover, a higher secretion of IL1β in endometrial cancer patients compared to healthy tissues correlates with infiltrating CD56bright NK cells in the tumor with exhausted phenotype, indicated by TIGIT and TIM3 expression." (PMID 34447383, 2021). "We found that both tumour and microenvironment-derived IL-1B drive the infiltration of immune cells which may harbour anti-tumour functions in breast primary tumours, however, in bone, IL-1B supports metastasis formation." (PMID 34290237, 2021). "However, the involvement of IL1β, particularly tumor cell IL1β crosstalk with normal resident myofibroblasts, either at a primary site (NCFs) or at a distant niche (NHFs), altering the sensitivity to cytotoxic chemotherapy has not been described." (PMID 34066976, 2021). "Additionally, IL-1β enhances tumor cell invasion through supporting the production of matrix-degrading enzymes (e.g., matrix metalloprotease 9 (MMP-9)) as well as through activation of the Src/FAK pathway." (PMID 33809315, 2021). "In breast cancer models, TAMs secreted IL-1β induce γδ T cells release IL-17 to regulate the release of G-CSF and promote the recruitment of neutrophils to stimulate metastasis, indicating that TANs is closely related to TAMs in tumor progression." (PMID 34625124, 2021). "Nuclear factor kappa beta and STAT3 hyperactivation in tumor cells and immune cells in the tumor microenvironment in turn promotes production of several pro-inflammatory cytokines including IL-1β, IL-6, and TNFα, which promote survival and proliferation of tumor cells." (PMID 35048057, 2021). "First, coculture with tumor cells inhibited the expression of M1-related genes encoding IL-6, TNF-α, and IL-1β and increased the expression of M2-related genes encoding CD163, Arg1, IL-10, TGF-β, and VEGFA, as well as expression of TNF-α and CD163 at protein level." (PMID 34093857, 2021). "For instance, in basal-like, transcriptional reprogramming of tumor-infiltrating myeloid cells was mediated in part by IL-1β induced NF-kB activation, indicating that this subtype can adapt to and take advantage of inflammatory signaling to grow and metastasize." (PMID 33840390, 2021). "And since IL-1β is involved in tumor pathological rather than physiological lymphangiogenesis, the side effects of targeting IL-1β to block tumor lymphangiogenesis may be limited." (PMID 34602858, 2021). "Nonetheless, the expression of inhibitory and suppressive markers, including genes for IL-4R, IL-10, IL-6, VEGFA, CCL2 and IL-1β, were mostly expressed by cluster 0, suggesting that these cells had a tumor-promoting and immune-suppressing functions, which resemble MDSC-like cells." (PMID 34025646, 2021). "In TNBC, the increase of IL-1β directly affects the invasiveness of tumor cells." (PMID 34602858, 2021). "Moreover, polyphenols exhibited the capacity to suppress tumor growth by reducing NF-kβ activity and IL-1β secretion." (PMID 34827151, 2021). "Taken together, these findings suggest that microenvironment-derived IL-1B may control breast primary tumour growth by driving an innate immune response, with potential anti-tumour functions." (PMID 34290237, 2021). "IL-1β is also reported to mediate anti-tumor responses through T lymphocytes." (PMID 33959494, 2021).
tumor (continued). "Moreover, IL-1β activated IRAK4 in cancer-associated fibroblasts, and then drove tumor fibrosis, chemoresistance, and poor prognosis in pancreatic cancer." (PMID 35360412, 2021). "Although Il1β can generate an adaptive anti-tumor immune response, following ablation it may produce a pro-tumor inflammatory response that ultimately results in MDSC recruitment and induction." (PMID 33441763, 2021). "Similarly, IL-1β was downregulated in HCC tumor tissues and cell lines compared with normal tissues and LO2 cells." (PMID 34546972, 2021). "We hypothesize that IL1B released from TAMs triggers elevated expression of ELF3 in LUAD tumor cells." (PMID 33144684, 2021). "Moreover, Th9 cells differentiated in presence of TGFβ and IL-4 harbor higher anti-tumor activity when IL-1β is present." (PMID 33498483, 2021). "iNOS dependent anti-tumor TAMs skew the TME towards cytotoxicity through stimulating Th1 responses via secretion of CXCL9 and CXCL10, inducing cytotoxic CD8s through TNFα and IL1β, and direct killing of tumor cells through nitric oxide (NO) and Reactive Oxygen Species (ROS)." (PMID 34222022, 2021). "IL-1β expression plays an essential role in tumor progression and metastasis." (PMID 34572719, 2021). "We, therefore, investigated whether targeting IL-1B in combination with standard of care agents that have immune-modulatory effects impairs primary tumour growth as well as metastasis." (PMID 34290237, 2021). "IL-1β may participate in NLRP3 inflammasome-mediated tumor promotion in the tumor microenvironment since recombinant IL-1β treatment of macrophages increased the migration and invasion of melanoma cancer cells." (PMID 33534121, 2021). "Thus, tumor-derived IL1β induces accumulation of MDSCs that impair NK cell development and functions." (PMID 34447383, 2021). "IL-1β and IL-18 can promote carcinogenesis and tumor progression by inducing inflammation." (PMID 34104103, 2021). "However, while a marker of immunosuppressive macrophages, MARCO engagement led to the expression of the pro-inflammatory genes Tnf, Il1b, and Nos2, leading to reduced primary tumor growth and metastases." (PMID 34572013, 2021). "In bone metastasis, IL-1B displays a tumour-supportive function and may control myeloid cell number." (PMID 34290237, 2021). "Paracrine crosstalk mediated by tumor-derived IL1β and CAFs was also described." (PMID 34066976, 2021). "Increased levels of IL-1β can promote angiogenesis and tumor progression." (PMID 33799622, 2021). "Furthermore, IL-1β was found to be elevated in CRC tumors, which was mainly secreted by tumor-associated macrophages." (PMID 34667160, 2021). "Within the bcl-2-driven protumor reprogramming, IL-1β acts as critical upstream regulator of tumor growth and macrophage functions, since its neutralization decreased the expression of COX-2 and IL-17, as well as expression of M2 polarization markers by macrophages." (PMID 32269145, 2020). "However, the authors reported that the anti-tumor effect of IL-1β-induced-Th9 cells relied on IL-21 since the neutralization of IL-9 had a minor impact on anti-tumor properties under this circumstance." (PMID 32508847, 2020). "IL-1β has been proven to promote the angiogenesis and stemness of tumor cells." (PMID 32983146, 2020). "Additionally, pro-inflammatory markers (e.g., IL1α and IL1β) were highly expressed at the tumour periphery, while a more anti-inflammatory phenotype (e.g., IL1RN) was observed in the tumour core." (PMID 31973030, 2020). "However, due to its key role as a downstream mediator of inflammation, IL-1β has been shown to have tumor-promoting, as well as anti-tumorigenic effects." (PMID 32516941, 2020). "Moreover, the NLRP3 inflammasome was shown to promote tumor growth in models of carcinogen-induced sarcoma and skin papilloma through the release of IL-1β." (PMID 33042810, 2020).
tumor (continued). "The main experimental evidence comes from the mouse model of IL-1β ablation that displayed reduced tumor growth compared to the wild-type, while in knock-out mice for the antagonist IL-1Ra, the tumor developed rapidly and with a sparse leukocyte infiltrate at the site of carcinogen injection." (PMID 32825489, 2020). "Accordingly, P2X7R-/- DCs produced less IL-1β when cultured with tumor cells than wild-type DCs." (PMID 32668623, 2020). "In this context, targeting tumor and host-derived IL-1β with anakinra improves anti-PD-1 therapy." (PMID 33261061, 2020). "Testing combinations of various cytokines in T cell culture media revealed that tumor antigen specific CD4+ T cell growth was improved by culturing in IL-1β, IL-2, IL-6, IL-7, IL-15, IL-21, IL-23, and TGFβ, and that the addition of TGFβ was critical for the improved performance of the cocktail." (PMID 33362774, 2020). "Interestingly, the most abundant cytokine–receptor pair interaction between TAMs and tumor cells was predicted for IL1B and its decoy receptor IL1R2, suggesting the inhibition of IL1B-mediated proinflammatory signaling by tumor cells." (PMID 33277616, 2020). "Strikingly, knockdown of IL‐1β and block IL‐1R could eliminate cell apoptosis, suggesting that IL‐1β acts as a strong death‐promoting factor in destroying intact wall structure of sinusoids during tumor cell metastasis." (PMID 33252861, 2020). "Anticancer effects of these compounds and their combination with cisplatin were assessed in this tumor mouse model with bioluminescent signaling and histopathology, and a cytokine assay was used to examine expression of inflammatory cytokines IL-1β, IL-6, IL-10, and TNF-α from plasma samples." (PMID 32174830, 2020). "Further, DHA significantly reduced the expression of IL-1β in xenograft tumor microenvironment." (PMID 32577124, 2020). "SAA may also favor tumor development by limiting immune anti-tumor by stimulating the growth of regulatory T cells in a process involving IL-1β and IL-6 induction in monocyte." (PMID 32517794, 2020). "Interestingly, 15 genes related to CRC progression, 19 genes related to cell migration and 17 genes related to NF-kB/IL-1β-mediated recruitment of MDSCs were upregulated in tumor-infiltrating PMN-MDSCs." (PMID 31941522, 2020). "Finally, IL1b can be released by brain microglia and infiltrating peripheral macrophages and promotes tumor growth, endothelial cell activation, tumor angiogenesis and further induction of immunosuppressive cells, through NF-kB and MAPK pathways." (PMID 33066172, 2020). "In this study, the expression of IL-1β was obviously increased in PRDX4 Tg tumor microenvironment." (PMID 33456675, 2020). "In addition, treatment with IL-1 RA resulted in the essentially similar responses, suggesting that inflammasomes activation and IL-1β secretion have a tumor promoting effect." (PMID 32155890, 2020). "IL-1β treatment led to a significant increase in tumor growth both in vitro and in vivo." (PMID 32547321, 2020). "According to previous studies, IL-1β promotes 4T1 tumor growth." (PMID 33042810, 2020). "Therefore, it is possible that the molecular relationships between RORγt and IL-17A, IL-23 and IL-1β seen on lymphocytes cannot be extrapolated to tumor cells." (PMID 32139737, 2020). "Most cancers evade immune supervision by impairing the functions of immune cells, such as tumor associated neutrophils, regulatory T cells, marrow‐derived suppressor cells, tumor‐associated macrophages and/or by releasing inhibitory cytokines, such as GM‐CSF, VEGF, IL‐1β and chemokines." (PMID 32935479, 2020). "Therefore, a possible explanation to our observation is that necroptotic IL-1β activates NF-κB pathway in treated tumor cells and further leads to increased migration and invasion." (PMID 32444644, 2020). "In short, DHA reduced IL-1β secretion in the serum from nude mice with xenograft tumor." (PMID 32577124, 2020).